SHC1 (SHC adaptor protein 1)
Description:
Signaling adapter that couples activated growth factor receptors to signaling pathways. Participates in a signaling cascade initiated by activated KIT and KITLG/SCF. Isoform p46Shc and isoform p52Shc, once phosphorylated, couple activated receptor tyrosine kinases to Ras via the recruitment of the GRB2/SOS complex and are implicated in the cytoplasmic propagation of mitogenic signals. Isoform p46Shc and isoform p52Shc may thus function as initiators of the Ras signaling cascade in various non-neuronal systems. Isoform p66Shc does not mediate Ras activation, but is involved in signal transduction pathways that regulate the cellular response to oxidative stress and life span. The expression of isoform p66Shc has been correlated with life span (By similarity). Participates in signaling downstream of the angiopoietin receptor TEK/TIE2, and plays a role in the regulation of endothelial cell migration and sprouting angiogenesis. Involved in the oncostatin-M-mediated signaling pathway through type II OSM receptor complex (heterodimers composed of OSMR and IL6ST) where it contributes to activation of the Ras/Raf/MAPK pathway through JAK1-dependent recruitment to OSMR subunit of OSMR complex and SHC1 association with GRB2.
Synonyms: SHC; SHCA; p66
Tractability: Small molecule: it has a high-quality binding pocket. Antibody: its Gene Ontology location is reachable by antibodies, with high confidence. PROTAC: ubiquitination databases record sites on it; its protein half-life has been measured; a small molecule that binds it is known.
Gene: Protein-coding gene on chromosome 1 (154,962,284 to 154,974,395, reverse strand). Ensembl gene ENSG00000160691.
Subcellular location: Cytoplasm; Cell junction, focal adhesion; Mitochondrion matrix (Isoform p46Shc); Mitochondrion (Isoform p66Shc)
Subcellular location (Human Protein Atlas): Cytosol
Pathways (Reactome):
Signal Transduction: Activated NTRK2 signals through RAS; Activated NTRK3 signals through RAS; Erythropoietin activates RAS; Extra-nuclear estrogen signaling; GPER1 signaling; Insulin receptor signalling cascade; Integrin signaling; MET activates RAS signaling; RAF/MAP kinase cascade; SHC-mediated cascade:FGFR1; SHC-mediated cascade:FGFR2; SHC-mediated cascade:FGFR3; SHC-mediated cascade:FGFR4; SHC-related events triggered by IGF1R; SHC1 events in EGFR signaling; SHC1 events in ERBB2 signaling; SHC1 events in ERBB4 signaling; Signal attenuation; Signaling by ALK; Signaling by LTK; Signalling to RAS
Immune System: DAP12 signaling; FCERI mediated Ca+2 mobilization; FCERI mediated MAPK activation; Interleukin receptor SHC signaling; Interleukin-15 signaling; Interleukin-2 signaling; Interleukin-3, Interleukin-5 and GM-CSF signaling; Role of LAT2/NTAL/LAB on calcium mobilization; Signaling by CSF1 (M-CSF) in myeloid cells; Signaling by CSF3 (G-CSF)
Disease: Constitutive Signaling by EGFRvIII; Constitutive Signaling by Ligand-Responsive EGFR Cancer Variants; Constitutive Signaling by Overexpressed ERBB2; Signaling by ALK fusions and activated point mutants; Signaling by ERBB2 ECD mutants; Signaling by ERBB2 KD Mutants; Signaling by ERBB2 TMD/JMD mutants
Cellular responses to stimuli: XBP1(S) activates chaperone genes
Developmental Biology: RET signaling
and 1 more pathways
Gene Ontology:
Molecular function: ephrin receptor binding; insulin receptor binding; insulin-like growth factor receptor binding; neurotrophin TRKA receptor binding; phosphotyrosine residue binding; protein binding; epidermal growth factor receptor binding; phospholipid binding; receptor tyrosine kinase binding; transmembrane receptor protein tyrosine kinase adaptor activity; epidermal growth factor binding
Biological process: cellular response to growth factor stimulus; defense response to bacterium; negative regulation of apoptotic process; negative regulation of DNA-templated transcription; positive regulation of DNA-templated transcription; positive regulation of MAPK cascade; epidermal growth factor receptor signaling pathway; insulin receptor signaling pathway; positive regulation of cell population proliferation; insulin-like growth factor receptor signaling pathway; intracellular signal transduction
Cellular component: cytosol; plasma membrane; Shc-EGFR complex; cytoplasm; focal adhesion; mitochondrial matrix; mitochondrion
Genetic constraint (gnomAD): Loss-of-function variants: 28 observed, 54.42 expected, observed/expected ratio (o/e) 0.51, 90% interval 0.38 to 0.7. The upper end of that interval is the gene's LOEUF score, 0.7, which puts it in group 2 of 6, group 1 being the genes least tolerant of losing a copy. Missense variants: 668 observed, 790.47 expected, observed/expected ratio (o/e) 0.85, 90% interval 0.79 to 0.9. Synonymous variants: 304 observed, 316.68 expected, observed/expected ratio (o/e) 0.96, 90% interval 0.87 to 1.06.
Homologues: Orthologues: chimpanzee SHC1 (99% identical), macaque SHC1 (99% identical), pig SHC1 (97% identical), dog SHC1 (94% identical), guinea pig SHC1 (94% identical), mouse Shc1 (94% identical), rat Shc1 (94% identical), rabbit SHC1 (79% identical), tropical clawed frog shc1 (74% identical), zebrafish shc1 (61% identical). Paralogues in human: SHC3 (48% identical), SHC4 (48% identical), CEP152 (18% identical).
Diseases named in the same sentence as SHC1 in open-access papers:
SHC1 is named in the same sentence as 90 diseases in open-access papers, as found by Europe PMC text mining. Sharing a sentence is not in itself a finding about the gene and the disease. The quoted sentences say what the papers report.
breast cancer (36 papers, 2008 to 2025). A primary or metastatic malignant neoplasm involving the breast. "SHC1 encodes a splice protein that acts on various tyrosine kinase signaling pathways and is thought to be a key mediator in promoting immunosuppressed breast cancer." (PMID 35686121, 2022). "SHC1 encoding protein is recruited to tyrosine kinases, which is essential for breast cancer initiation, progression, and metastasis." (PMID 33679866, 2020). "The SHC1 gene encodes an adaptor protein that functions as a central regulator of various tyrosine kinase signaling pathways, and was proposed as a key mediator of breast cancer by promoting immune suppression." (PMID 32028264, 2020). "It has implicated that SHC1 mediate several key signaling pathways in breast cancer." (PMID 33679866, 2020). "It is important to note that in our analysis, if using gene mutation data alone, none of the genes in the positively regulating FFL would have been identified, since the mutation frequency of PDGF-D, FLT1, and SHC1 are very low across all breast cancer samples." (PMID 28392480, 2017). "The predictive power of the FFL (PDGF/FLT1/SHC1) in the PIK3CA-mutated luminal-A tumor patients demonstrated in this study could be further validated in other breast cancer cohorts when genome sequencing data for these cohorts are available in the future." (PMID 28392480, 2017). "Importantly, mammary tumor progression of Shc1 deficient hyperplasias is significantly accelerated in athymic mice compared to immunocompetent animals, suggesting that Shc1 signaling suppresses T cell immune responses, ultimately facilitating tumor progression." (PMID 33807608, 2021). "For these reasons, we generated the first animal models for Shc1-isoform-specific knockout of the p52SHC (p52SHCKO) isoform and first rat knockout of p66SHC (p66SHCKO) isoform in the SS/JrHsdMcwi (SS) genetic background, which is a well-studied rat parental background for breast cancer risk." (PMID 31202267, 2019). "Recent research has indicated that the SHC1 gene has a significant impact on different types of tumors, including breast cancer and gastric cancer." (PMID 37965333, 2023). "With further study on SHC1, it has been found that the SHC1 gene plays an important role in the growth of breast cancer, gastrointestinal tumor cells, and other tumor cells." (PMID 35706930, 2022). "Recent reports indicated that SHC1 was a key driver of breast cancer initiation, and the SHC1 adaptor simultaneously balanced Stat1 and Stat3 activity to promote breast cancer immune suppression." (PMID 35935986, 2022). "Taken together, these results show that SHC1 plays a key role in immune escape and immunosuppression in breast cancer." (PMID 35601500, 2022). "A previous study showed that tyrosine kinases require downstream SHC1 signaling to evade anti-tumor immunity in breast cancer." (PMID 35601500, 2022). "The p66ShcA redox protein is the longest isoform of the Shc1 gene and is variably expressed in breast cancers." (PMID 31941526, 2020). "Several lines of evidence suggest the direct involvement of products of the Shc1 gene in the regulation of breast cancer initiation and progression in this model." (PMID 31202267, 2019). "Immunohistochemical staining of SHC1 proteins showed markedly elevated expression of SHC1 proteins in breast cancer cells compared to adjacent normal breast epithelia or stromal cells, both in human and rat tumors." (PMID 31202267, 2019). "Compared with WT tumors, 893 differentially expressed (DE; FDR < 0.05) genes were detected in p52SHC KO tumors compared with only 18 DE genes in the p66SHC KO tumors, further highlighting that p52SHC is the relevant SHC1 isoform in breast cancer." (PMID 31202267, 2019). "We previously identified the Shc1 (ShcA) scaffold, a central regulator of tyrosine kinase signalling, as essential for promoting breast cancer immune suppression." (PMID 28276425, 2017).
breast cancer (continued). "Here, the authors show that tyrosine kinases engage scaffold protein Shc1 to promote immunosuppression in breast cancer by simultaneously activating STAT3 immunosuppressive signals and impairing STAT1-driven anti-tumour immune responses." (PMID 28276425, 2017). "By combining affinity capture using matured antibodies to SHC1 with mass spectrometry, we identified seven known binding partners and two known SHC1 phosphorylation sites in epidermal growth factor (EGF)-stimulated human breast cancer epithelial cells." (PMID 21704603, 2011). "With this in mind, we developed a novel 96-well immunocapture screen to rapidly identify binders recognizing available epitopes with sufficient affinity to capture low levels of endogenous SHC1 in a breast cancer epithelial cell line." (PMID 21704603, 2011). "We examined the level of SHC1 phosphoprotein (NP_001123512.1, S139, Y428, and S454 sites) between normal and six types of tumor tissues (breast cancer, UCEC, ovarian cancer, lung adenocarcinoma, colon cancer, and clear cell RCC) based on the CPTAC dataset, using the UALCAN web resource." (PMID 35601500, 2022). "Many studies have implicated SHC1 involvement in signaling by epidermal growth factor receptor-2 (HER-2), estrogen receptor (ER), and prolactin (PR) signaling, three well-established biological markers for prognosis and response to breast cancer therapy." (PMID 31202267, 2019). "Furthermore, increased expression of Shc1 gene products have been shown to accelerate tumorigenesis in the MT antigen model, indicating its importance in this model of breast cancer." (PMID 31202267, 2019). "According to the Human Protein Atlas, in breast carcinomas, there is a difference in expected outcome between patients expressing high levels of SHC1 RNA and patients expressing low levels of SHC1 RNA based on best separation (P = 0.0412), but not median separation (P = 0.0928)." (PMID 31202267, 2019). "To focus on antibodies with this property, we developed a 96-well plate-based affinity capture screen that enabled the screening of hundreds of clones simultaneously for their ability to bind endogenous full-length SHC1 from a breast cancer epithelial cell lysate." (PMID 21704603, 2011). "Therefore, in vitro test on breast cancer cells harboring the active FFL (PDGF/FLT1/SHC1) using small molecule inhibitor drugs such as sunitinib, which also targets the PDGF receptors, could be an interesting validation experiment in the future." (PMID 28392480, 2017). "Our proteomic analysis revealed proteomic profile alteration in MDA-MB-231 upon CB exposure that potentially led to breast cancer suppression, such as ZPR1/SHC1/MAPK-mediated cell proliferation and AXL/VAV2/RAC1-mediated cell motility pathways." (PMID 39527598, 2024). "This is partially mediated by tyrosine 239/240 and tyrosine 313 residues of Shc1, which activate STAT3-dependent immunosuppression and inhibit STAT1-induced immune surveillance in breast cancer cells, respectively." (PMID 33807608, 2021). "We found that the vast majority of IGF regulators were upregulated in various cancers, such as HRAS and YWHAZ in lung squamous cell carcinoma (LUSC), SHC1 in kidney cancer, PRKCZ in bladder cancer (BLCA) and in breast cancer (BRCA), and NCK2 in cholangiocarcinoma (CHOL)." (PMID 35935986, 2022). "Even though these data suggest the significance of high levels of SHC1 RNA for the worst expected outcome of breast cancer, they do not address the impact of individual protein isoforms in the progression of breast carcinomas." (PMID 31202267, 2019). "Despite the broad evidence implicating SHC1 gene products as a central mediator of breast cancer, testing the isoform-specific roles of SHC1 proteins have been inaccessible due to the lack of isoform-specific inhibitors or gene knockout models." (PMID 31202267, 2019).
breast cancer (continued). "Western blot analysis of SHC1 isoforms expression in WT and genetically modified rat spleen tissue, freshly isolated mammary tissue fragments and DMBA-induced mammary tumor (B)." (PMID 31202267, 2019). "SHC1 proteins (also called SHCA) exist in three functionally distinct isoforms (p46SHC, p52SHC, and p66SHC) that serve as intracellular adaptors for several key signaling pathways in breast cancer." (PMID 31202267, 2019). "Moreover, many studies revealed that SHC1 participated in signalling through epidermal growth factor receptor‐2 (HER‐2), oestrogen receptor (ER) and prolactin (PR) signalling, which were well‐recognized biological markers for predicting prognosis and response to breast cancer therapy." (PMID 34117717, 2021).
lung carcinoma (16 papers, 2010 to 2025). "Significantly, the analysis showed that SHC1 methylation level was associated with OS in lung cancer patients." (PMID 34117717, 2021). "In order to explore the relevance and underlying mechanisms of SHC1 expression in lung cancer, we investigated the different prognostic factors in lung cancer via the KM Plotter database." (PMID 34117717, 2021). "Additionally, our data revealed that SHC1 methylation was associated with OS in lung cancer patients although multiple probes showed individual differences." (PMID 34117717, 2021). "Despite the previous evidence showing that SHC adaptor protein 1 (SHC1) could encode three distinct isoforms (p46SHC, p52SHC and p66SHC) that function in different activities such as regulating life span and Ras activation, the precise underlying role of SHC1 in lung cancer also remains obscure." (PMID 34117717, 2021). "Among the signature genes identified in this study, SHC1 expression was significantly increased in patients with lung cancer, and its expression level and methylation level were associated with survival." (PMID 38602568, 2024). "Recent studies have confirmed that SHC1 interacts to form protein complexes to promote the progression of lung cancer." (PMID 36969076, 2023). "The results showed that differential expression of SHC1 influenced the overall survival of lung cancer patients." (PMID 35706930, 2022). "The results showed that silencing SHC1 inhibited the proliferation and invasion of lung cancer cells." (PMID 35706930, 2022). "In order to further study the effect of SHC1 on lung cancer, we conducted animal experiments by subcutaneous tumor loading in nude mice." (PMID 35706930, 2022). "The expression of SHC1 in lung cancer and adjacent tissues was analyzed by bioinformatics and immunohistochemistry." (PMID 35706930, 2022). "The study aims to explore the biological function of SHC1 in the development and progression of lung cancer." (PMID 35706930, 2022). "Compared with human normal lung epithelial cells BEAS-2B, SHC1 expression was higher in lung cancer cell lines A549, NCI–H446, NCI–H460, and NCI–H292." (PMID 35706930, 2022). "The results of statistical analysis showed that the high expression of SHC1 in lung cancer was statistically significant." (PMID 35706930, 2022). "This is the first study to show SHC1 is upregulated in brain and CNS cancers, head and neck cancers, kidney cancer, liver cancer, lung cancer, melanoma, and prostate melanoma using the Oncomine database." (PMID 35601500, 2022). "Overexpression of SHC1 was correlated with poorer OS in female lung cancer patients (OS HR = 1.79, logrank P < 0.01)." (PMID 34117717, 2021). "Our results revealed that these two subtypes of lung cancer showed higher differences in SHC1 methylation." (PMID 34117717, 2021). "A total of 577 lung cancer patients with higher SHC1 expression were stage 1 at diagnosis (577/891, 64.76%)." (PMID 34117717, 2021). "Another study revealed that NRF2 regulated the expression of p66Shc (SHC1 isoform) in human lung cancer cells." (PMID 31884422, 2019). "Currently, there are few studies on the expression and biological effects of SHC1 in lung cancer." (PMID 35706930, 2022). "In conclusion, SHC1 plays a carcinogenic role in lung cancer." (PMID 35706930, 2022). "In this study, the mechanism of SHC1 in the development and progression of lung cancer was studied." (PMID 35706930, 2022). "Lung cancer patients with high SHC1 expression have a poor prognosis." (PMID 35706930, 2022). "First, SHC1 knockout lung cancer cell lines were constructed." (PMID 35706930, 2022). "In conclusion, we highlighted SHC1 clinical significance and its methylation in lung cancer." (PMID 34117717, 2021). "In addition, high SHC1 expression lung cancer patients had poorer OS in the American Joint Committee on Cancer (AJCC) stage M0 (OS HR = 1.31, logrank P = 0.0114) while the patient number was not enough for meaningful analysis in AJCC stage M1." (PMID 34117717, 2021).